SIRT2 (sirtuin 2)
Diseases named in the same sentence as SIRT2 in open-access papers (continued):
Sharing a sentence is not in itself a finding about the gene and the disease.
osteosarcoma (continued). "We then knocked down Snail in SIRT2-overexpressing cells and showed that Snail knockdown abrogated the promoting effect of SIRT2 on the migration and invasion of osteosarcoma cells, suggesting that SIRT2 promotes the invasion and metastasis of osteosarcoma cells via Snail." (PMID 36344502, 2022). "Therefore, SIRT2 might be a promising candidate for use against the metastasis of human osteosarcoma." (PMID 36344502, 2022). "SIRT1, SIRT2, SIRT6 and SIRT7 proteins are mainly localized in the nucleus or cytoplasm and are more likely to play important roles in the development of osteosarcoma." (PMID 36344502, 2022). "However, the underlying molecular mechanisms of SIRT2 in osteosarcoma cell metastasis and the question of whether SIRT2 regulates EMT have not been fully explored." (PMID 36344502, 2022). "Therefore, SIRT2 might be a promising therapeutic target for treating osteosarcoma." (PMID 36344502, 2022). "To clarify the regulatory relationship between SIRT2 and Snail, we detected the expression of Snail in osteosarcoma cells, and Snail expression was upregulated in MG63 and Saos-2 cells (with high SIRT2 expression) compared with hFOB1.19 control cells (with low SIRT2 expression)." (PMID 36344502, 2022). "There are many studies on SIRT2 in breast cancer, liver cancer, lung cancer, leukemia and other malignant tumors, but no relevant research on its role in the development of osteosarcoma has been reported." (PMID 36344502, 2022). "We showed that the expression of SIRT2 but not SIRT1 was upregulated in osteosarcoma cells, which suggests that SIRT2 may contribute to the development of osteosarcoma." (PMID 36344502, 2022). "However, the expression of SIRT1 protein did not change greatly in osteosarcoma cells, which suggests that SIRT2 may play a more important role than SIRT1 in the development of osteosarcoma." (PMID 36344502, 2022). "However, the role of SIRT2 in senescence has not been well elucidated, although it is known that SIRT2 is involved in the stress-induced premature senescence, but not in the quiescence, of U2OS osteosarcoma cell line." (PMID 34856941, 2021).
periodontitis (3 papers, 2022 to 2025). An acute or chronic inflammatory process that affects the tissues that surround and support the teeth. "Immunohistochemical analysis revealed that the expression of SIRT2 in gingival tissues from periodontitis patients was significantly lower than in normal gingival tissues." (PMID 40606607, 2025). "Therefore, we hypothesize that SIRT2 may play a crucial role in the onset and progression of periodontitis by deacetylating CPT1A." (PMID 40606607, 2025). "In addition, SIRT2 was reported to be positively associated with NAMPT actions in human gingival fibroblasts, which was highly upregulated during periodontitis and engaged in osteoclast recruitment, inducing the expression of COX-2, matrix metalloproteinase (MMP)-1 and MMP-3." (PMID 36060706, 2022). "Overall, these findings demonstrate that SIRT2 binds to and deacetylates CPT1A, thereby inhibiting osteoclast differentiation and concurrently alleviating inflammation in periodontal tissues during experimental periodontitis progression." (PMID 40606607, 2025). "In addition, SIRT2 can downregulate CPT1A expression by deacetylating its CPT1A promoter, thereby partially delaying the progression of periodontitis." (PMID 40606607, 2025). "Nonetheless, the correlation between SIRT2 and FAO remains unknown, particularly in the context of periodontitis." (PMID 40606607, 2025).
psoriasis (3 papers, 2021 to 2023). An autoimmune condition characterized by red, well-delineated plaques with silvery scales that are usually on the extensor surfaces and scalp. "Preliminary experimental studies appear to be promising, but an evaluation of the role of SIRT2 modulation in psoriasis therapy requires clinical trials." (PMID 37445960, 2023). "In a mouse model of psoriasis, researchers observed decreased levels of SIRT2 and increased activation of PKM2 through the acetylation and phosphorylation of STAT3." (PMID 37445960, 2023). "There is a significant reduction in the expression of SIRT1, SIRT2, SIRT3, SIRT4 and SIRT5 and an increase in the expression of SIRT6 and SIRT7 in psoriasis." (PMID 37445960, 2023). "The role of SIRT2 in psoriasis has not been extensively explored." (PMID 37445960, 2023). "As a result, mice lacking SIRT2 exhibited more pronounced psoriasis." (PMID 37445960, 2023). "The dysregulation of this auto-regulatory loop could be also due to the abnormal expression of SIRTs in psoriasis, with the downregulation of SIRT1, SIRT2, SIRT3, SIRT4, and SIRT5 and upregulation of SIRT6 and SIRT7 in skin lesions skin, as previously reported." (PMID 34202251, 2021).
acute kidney injury (2 papers, 2018 to 2024). Sudden and sustained deterioration of the kidney function characterized by decreased glomerular filtration rate, increased serum creatinine or oliguria. "SIRT2 deficiency ameliorates lipopolysaccharide-induced acute tubular injury and suppresses renal failure with decreased renal Cxcl2 mRNA expression." (PMID 29651144, 2018).
acute liver failure (2 papers, 2024 to 2025). Rapid deterioration of liver function causing encephalopathy and coagulopathy. "Based on above results, our data have verified that SIRT2 plays a significant role in the progression of acute liver failure, influencing key pathways related to autophagy and autophagy." (PMID 39009648, 2024). "In conclusion, the data suggested the link between AMPK and SIRT2, and reveals the important role of AMPK and SIRT2 in autophagy on acute liver failure." (PMID 39009648, 2024). "In acute liver failure, the pathways by which SIRT2 regulates autophagy are unknown." (PMID 39009648, 2024). "This study explores the role of SIRT2 in regulating autophagy and its interaction with AMPK in the context of acute liver failure (ALF)." (PMID 39009648, 2024). "SIRT2 and AMPK are important for autophagy in acute liver failure." (PMID 41567643, 2025).
acute pancreatitis (2 papers, 2018 to 2023). An acute inflammatory process that leads to necrosis of the pancreatic parenchyma. "Sirt2-deficient mice showed prolonged inflammation in caerulein-induced acute pancreatitis, suggesting that these mice may have intrinsic problems with their immune response." (PMID 30405152, 2018). "Our results indicate that Sirt2 deficiency increases inflammation infiltration during caerulein-induced acute pancreatitis and strongly impairs the recovery from pancreatic tissue injury, as well as leads to the accumulation of oncogenic Kras mutations in the pancreas." (PMID 30405152, 2018). "Consistently, global Sirt2 knockout has been demonstrated to lead to prolonged fibrogenic responses in cerulein-induced mouse models of acute pancreatitis." (PMID 37777567, 2023). "Taken together, these results suggest that loss of Sirt2 led to delayed pancreas tissue recovery after caerulein-induced acute pancreatitis, suggesting SIRT2 may play role in pancreatic tissue regeneration." (PMID 30405152, 2018).
alcoholic liver diseases (2 papers, 2023). A disorder caused by damage to the liver parenchyma due to alcohol consumption. "For example, hepatic SIRT2 protein expression was inversely correlated with alcoholic liver disease development." (PMID 37485877, 2023).
amyloid (2 papers, 2023). "In agreement with recent studies using a different brain-permeable SIRT2 inhibitor, spatial learning, memory abilities and amyloid pathology were improved by 33i treatment in our study." (PMID 37698780, 2023). "We administered a SIRT2 inhibitor to APP/PS1 mice, a model for AD, and found beneficial effects in the CNS: improved memory and learning, decreased amyloid pathology, and reduced neuroinflammation." (PMID 38132302, 2023).
Arthritis (2 papers, 2021 to 2022). Inflammation of a joint. "SIRT2 has been implicated in the progress of inflammation in arthritis." (PMID 34344401, 2021).
autism (2 papers, 2019 to 2025). Persistent deficits in social interaction and communication and interaction as well as a markedly restricted repertoire of activity and interest as well as repetitive patterns of behavior. "In summary, our findings demonstrate that Rg1 counters VPA‐induced autism‐like behaviors—ranging from repetitive actions to impaired sociability—by modulating Sirt2/Foxo1 expression and reducing neuroinflammation and oxidative damage." (PMID 40622845, 2025). "This study investigated whether Ginsenoside Rg1 (Rg1) alleviates autism‐like behaviors in mice prenatally exposed to valproic acid (VPA) via Sirt2/Foxo1 signaling." (PMID 40622845, 2025).
autoimmune disorders (2 papers, 2024). "In addition, it would be of particular interest to selectively silence SIRT proteins in astrocytes in models of CNS pathologies since inactivation of SIRT1 and SIRT2 attenuated the pro-inflammatory phenotype of astrocytes in CNS autoimmunity and spinal cord injury, respectively." (PMID 38474102, 2024).
Cirrhosis (2 papers, 2023 to 2024). A chronic disorder of the liver in which liver tissue becomes scarred and is partially replaced by regenerative nodules and fibrotic tissue resulting in loss of liver function. "Chronic HBV infection is a major contributor to cirrhosis, with SIRT2 regulating fibrosis by affecting HBV replication and transcription." (PMID 39226168, 2024).
diabetic neuropathy (2 papers, 2022 to 2025). A chronic, pathological complication associated with diabetes mellitus, where nerve damages are incurred due to diabetic microvascular injury involving small blood vessels that supply these nerves, resulting in peripheral and/or autonomic nerve dysfunction. "Inhibiting the polyol pathway with specific inhibitors restored SIRT2 expression and improved mitochondrial function, suggesting that enhancing SIRT2 signaling could be a potential therapeutic strategy for diabetic neuropathy." (PMID 39835172, 2025).
epilepsy (2 papers, 2015 to 2022). A brain disorder characterized by episodes of abnormally increased neuronal discharge resulting in transient episodes of sensory or motor neurological dysfunction, or psychic dysfunction. "Remarkably, GluA1 hippocampal expression is altered during status epilepticus, MTLE patients show reduced hippocampal expression of Sirtuin-2, and endothelial barrier function is altered in epilepsy." (PMID 26011637, 2015). "In a rat model of pentylenetetrazole (PTZ)-induced epilepsy, we quantify 43 acylations in 29 cerebral cortex proteins; levels of NAD+; expression of NAD+-dependent deacylases (SIRT2, SIRT3, SIRT5); activities of the acyl-CoA-producing/NAD+-utilizing complexes of 2-oxoacid dehydrogenases." (PMID 36293175, 2022).
Fungal Infection (2 papers, 2021 to 2025). "Together, these data indicate that the deacetylase Sirt2 is a therapeutic target for the treatment of systemic fungal sepsis, and inhibitors of Sirt2 have the potential to be developed as drugs for the treatment of invasive fungal infection." (PMID 34301894, 2021). "Taken together, these results suggest that Sirt2 represents a potential target for antifungal drug development, and inhibitors of Sirt2 may have potential use as a therapy for patients with invasive fungal infection." (PMID 34301894, 2021). "As there is a Sirt2 inhibitor, AK-7, which can specifically cross the blood–brain barrier, we next examined whether AK-7 has any therapeutic effect on CNS fungal infection." (PMID 34301894, 2021). "Therefore, small compounds of the Sirt2 inhibitors AGK2, AK-1, or AK-7 have good therapeutic effects on invasive fungal infections." (PMID 40489568, 2025).
hepatitis B (2 papers, 2014 to 2021). "In the study of hepatitis B virus (HBV) infection, Sirt2 overexpression was associated with Akt activation, which consequently downregulated glycogen synthase kinase 3β (GSK-3β) and increased β-catenin levels." (PMID 34925016, 2021).
Impaired glucose tolerance (2 papers, 2018 to 2024). An abnormal resistance to glucose, i.e., a reduction in the ability to maintain glucose levels in the blood stream within normal limits following oral or intravenous administration of glucose. "Hepatic Sirt2 knockdown in non-diabetic mice reduces HGU and causes impaired glucose tolerance." (PMID 29296001, 2018).
injury (2 papers, 2021 to 2023). Damage inflicted on the body as the direct or indirect result of an external force, with or without disruption of structural continuity. "SIRT2 may exert pro-inflammatory actions in the kidneys because LPS-induced kidney injury in SIRT2 KO mice has a less severe course than in wild type mice." (PMID 34899370, 2021).
lupus (2 papers, 2023 to 2025). "In the context of autoimmune diseases, SIRT2 was shown to promote the development of systemic lupus erythematosus (SLE)." (PMID 39215785, 2025).
lymph node metastasis (2 papers, 2017 to 2020). "SIRT2 loss has been correlated with clinicopathological characteristics, including distant metastasis, lymph node metastasis and American Joint Committee on Cancer (AJCC) stage; this loss serves as an independent factor that indicates a poor prognosis for patients with CRC." (PMID 32697380, 2020). "The absence of SIRT2 was correlated with the American Joint Committee on Cancer (AJCC) stage, distant metastasis and lymph node metastasis in CRC." (PMID 32697380, 2020).
lymphoma (2 papers, 2020). A malignant (clonal) proliferation of B- lymphocytes or T- lymphocytes which involves the lymph nodes, bone marrow and/or extranodal sites. "SIRT2-specific inhibitors were found to be less toxic against these cell lines compared to lymphoma cell lines." (PMID 31973227, 2020). "Following our long-standing interest in anti-lymphoma agents, coupled with the need for isoform-selective sirtuin modulators, we launched a medicinal chemistry effort to identify SIRT2 selective cambinol analogs and evaluate cytotoxicity against B-cell lymphomas." (PMID 31973227, 2020).
mood disorder (2 papers, 2015 to 2019). A cognitive disorder a disturbance in which the person's mood is hypothesized to be the main underlying feature. "Adverse changes in SIRT2 expression have been reported in mood disorders, with a decrease in SIRT2 expression consecutive to a chronic stress." (PMID 31763032, 2019).
overnutrition (2 papers, 2018 to 2023). An imbalanced nutritional status resulting from excessive intake of nutrients. "In addition, SIRT2 is a critical negative regulator of adipogenesis, and this, along with overnutrition, could contribute to the increased fat mass observed in the HF-fed SIRT2 KO mice." (PMID 30533032, 2018).
pancreatitis (2 papers, 2018 to 2021). Inflammation of the pancreas. "Here, we report that after caerulein-induced pancreatitis, Sirt2-deficient mice exhibited an increased inflammatory phenotype and delayed recovery." (PMID 30405152, 2018). "Here, we report that after caerulein-induced pancreatitis, Sirt2-deficient mice exhibited an increased inflammatory phenotype and delayed pancreatic tissue recovery." (PMID 30405152, 2018). "For the pancreas, SIRT2-KO induces extensive pancreatic fibrosis in the caerulein-induced pancreatitis mouse model." (PMID 34642310, 2021). "In closing, our results demonstrate that mice lacking Sirt2 exhibit a pancreatic inflammation permissive phenotype, as well as accumulate oncogenic Kras mutations that is accelerated during recovery from caerulein-induced pancreatitis." (PMID 30405152, 2018). "Thus, we proposed that mice lacking Sirt2 might exhibit a pancreatitis permissive phenotype, as well as Kras mutations." (PMID 30405152, 2018). "In this regard, we have shown that pathologically obvious pancreatic tissue damage was observed at 7 days after the last injection of caerulein, which continued up to at least 6 weeks, suggesting that mice lacking Sirt2 exhibit a pancreatitis permissive phenotype." (PMID 30405152, 2018).
peritonitis (2 papers, 2014 to 2017). Inflammation of the peritoneum (tissue that lines the abdominal wall and covers most of the organs in the abdomen). "Finally, more frequent transmural infiltration of inflammatory cells was observed in the tunica serosa (peritonitis) and even in the mesenteric fat tissue (steatitis) of Sirt2−/− mice, while mural extension occurred less in Sirt2+/+ mice." (PMID 25072851, 2014).
preeclampsia (2 papers, 2019 to 2025). Preeclampsia is a hypertensive disorder of pregnancy that is characterized by new-onset hypertension with proteinuria presenting after 20 weeks of gestation, and depending on mild or severe forms may initially present with severe headache, visual disturbances, and hyperreflexia. "Whether the seasonal pattern of SIRT2 could be implicated in the varying incidence of preeclampsia throughout the year remains to be investigated." (PMID 31653981, 2019). "The mean maternal serum SIRT2 levels were significantly lower both in early-onset (4.5 ± 2.1 vs. 6.3 ± 0.9, p < 0.001) and late-onset preeclampsia (2.1 ± 0.6 vs. 6.3 ± 0.9, p < 0.001) than the healthy pregnancies." (PMID 39808389, 2025). "FoxO1 and SIRT2 may be biomarkers for early detection of preeclampsia and potential therapeutic targets in the pathophysiology of preeclampsia." (PMID 39808389, 2025). "This study aimed to investigate whether serum FoxO1 and SIRT2 concentrations differ between preeclampsia and normal pregnancy and also to compare these markers in early- and late-onset preeclampsia." (PMID 39808389, 2025). "The ROC curve analysis of maternal serum SIRT2 and FoxO1 concentration for predicting preeclampsia." (PMID 39808389, 2025).
progeria (2 papers, 2016 to 2023). "SIRT2 has also been implicated in the pathology of cancer, neurodegenerative diseases and progeria." (PMID 27875273, 2016). "The discordance between the present findings and previous work on a background of the BubR1 hypomorph progeria model likely relates to the relevance of the mechanistic role for SIRT2 in the stabilization of BubR1 protein." (PMID 38009412, 2023). "Transgenic overexpression of SIRT2 in the BubR1 hypomorph model of progeria can rescue many aspects of health and increase overall lifespan, due to a specific interaction between SIRT2 and BubR1 that improves the stability of this protein." (PMID 38009412, 2023). "Previous work showed that SIRT2 overexpression could drastically rescue overall lifespan in a progeria mouse model, and we also showed that this same strain of SIRT2‐Tg mice had improved oocyte quality and female fertility later in life." (PMID 38009412, 2023).